CD68 (CD68 molecule)
Diseases named in the same sentence as CD68 in open-access papers (continued):
Sharing a sentence is not in itself a finding about the gene and the disease.
Granuloma (68 papers, 2007 to 2025). A compact, organized collection of mature mononuclear phagocytes, which may be but is not necessarily accompanied by accessory features such as necrosis. "We positively identified CTSZ within granuloma-associated CD68+ macrophages from Mtb-infected lung tissue." (PMID 40924769, 2025). "Histological analysis revealed that CD200R was expressed on CD68+ macrophages associated with granuloma." (PMID 38745652, 2024). "CD4+ T-cells constituted the main lymphocytic component of the granulomas and were closely associated with the CD68+ macrophages in the central core." (PMID 18477401, 2008). "Importantly, this defect in lipid metabolism is consistent with the spatial transcriptomic profile of granuloma-associated CD68 + cells." (PMID 36302964, 2022). "The granulomas within NTMD predominantly express CD68 and CD206, contrasting with the CD163 expression found in non-granulomatous areas, indicating distinct subpopulations with different roles." (PMID 41189710, 2025). "C4d depositions have been found in the central necroses and surrounding palisading CD68-positive macrophages in other diseases where granulomas are present such as rheumatic noduli and granuloma annulare." (PMID 40045390, 2025). "Here, granulomas from animals with limited pathology showed significantly elevated interactions between NK cells and macrophage subsets with a CD68+ tissue-resident macrophage phenotype in comparison to granulomas from animals with more severe pathology." (PMID 40749077, 2025). "In contrast to the circulating monocytes, CD200R was highly expressed on CD68+ cells located on the periphery of granulomas." (PMID 38745652, 2024). "Spatial protein analysis showed that granulomas in all diseases expressed CD68, CD11c, CD44, CD127, and PD-L1." (PMID 39373788, 2024). "In pleural biopsies, widespread STAT1 phosphorylation was seen in CD68+ cells, which are generally found in the core of organized granulomas." (PMID 38995971, 2024). "Frequencies of BODIPY-positive CD68+ macrophages were also higher in the granuloma areas of the lesional skin compared to the remaining tissue as well as to non-lesional skin." (PMID 38353578, 2024). "In the current study, immunohistochemistry (IHC) was used to investigate the expression of CD68, iNOS, and HLA-DR within different stages of TB granulomas in naturally tuberculosis-infected cattle." (PMID 37865747, 2023). "In granulomatous skin disease, FBP1 expression was detected in CD68-positive granuloma regions, while CD163 was observed surrounding FBP1-positive regions." (PMID 38038136, 2023). "Immunohistochemistry for CD68 showed diffuse cytoplasmic expression in macrophages, epithelioid macrophages, and Langhans MNGCs in all stages of granuloma." (PMID 37865747, 2023). "The location of these cells differed between stages, thus, while CD68+ macrophages were dispersed throughout stage I and stage II granulomas, in stages III and IV there was an obvious rim of positively stained macrophages surrounding the necrotic center." (PMID 37865747, 2023). "The granuloma structure characterization found in both patient biopsies was carried out via immunohistochemistry (IHC) using anti-CD68, anti-CD163 and anti-CD3, or anti-CD8 antibodies as markers of the monocyte/macrophage and lymphocyte lineages, respectively." (PMID 38067175, 2023). "CD68-reactivity has additionally been shown in GC cholesterol granulomas, a subtype of foreign body granulomas." (PMID 37509363, 2023). "Selected samples that yielded a positive result for ZN and mycobacterial culturing were subjected to an immunohistochemical study of CD68, iNOS, and HLA-DR expression by macrophages according to granuloma stages." (PMID 37865747, 2023). "iNOS expression followed a similar trend as CD68+ cells, with iNOS+ macrophages seen as dispersed throughout stages I and II granulomas and in a distinct ring encircling the necrotic core in stages III and IV granulomas." (PMID 37865747, 2023).
Granuloma (continued). "Immunohistochemical analysis revealed that the immunolabeling of CD68+, iNOS+, and HLA-DR+ macrophages significantly reduced as the stage of granuloma increased from stage I to stage IV (P < 0.003, P < 0.002, and P < 0.002, respectively)." (PMID 37865747, 2023). "Our data revealed that granulomas were mainly composed of CD68 and, to a lesser extent, of CD163 monocytes/macrophages and of CD3 T-lymphocytes." (PMID 38067175, 2023). "CD68 expression was observed within the cytoplasm of macrophages, epithelioid macrophages, and Langhans MNGCs at all stages of granuloma." (PMID 37865747, 2023). "Immunohistochemistry of sarcoidosis skin samples showed positivity for TREM2 and FBP1, which is consistent with the accumulation of CD68-positive cells in granuloma areas." (PMID 38038136, 2023). "When compared to granuloma periphery or mucosa, CD68+ cells in the granulomata demonstrated increased gene expression in lysosome or macrophage-related genes such as CTSD, CD68, HEXB, ATP6V0A1, CTSK, LIPA, CD63." (PMID 36302964, 2022). "As granulomas progress from stages I-IV an initial collection of CD68+ macrophages and CD68+ MGCs becomes a mixture of macrophages, MGCs and lymphocytes." (PMID 35056009, 2022). "Tophus was observed as a crystalline mass of MSU and neutrophil extracellular traps (NETs) similar to granulomas and encapsulated CD68+ macrophages, fibroblasts, and giant cells that contribute to the destruction of surrounding tissues." (PMID 35400961, 2022). "Inconceivably, ECs from TT granulomas exhibited the M1 phenotype (CD68+ CD163−), whereas Mφs in LL granulomas showed the M2 phenotype (CD68+ CD163+)." (PMID 34899703, 2021). "At week four post infection, cynomolgus macaques were found to have more CD68+ cells than rhesus in all but category 1 granulomas." (PMID 35069548, 2021). "At 4 wpc, a higher number of CD68+ macrophages were present in granuloma types from CM compared to those from RM in all but category 1 granulomas where numbers were equal in both species." (PMID 35069548, 2021). "Pulmonary granulomas from rhesus and cynomolgus macaques from two timepoints post infection were categorised into categories 1 – 6 (early to late stage granulomas) and immunohistochemistry was used to identify CD68+ macrophages, CD3+ T cells and CD20+ B cells." (PMID 35069548, 2021). "Overall, an increasing trend in the number of CD68+ macrophages from category 1 to category 5 granulomas was observed, with the highest numbers noted in the latter." (PMID 35069548, 2021). "The IHC analysis with antibodies to CD68 revealed that the granulomas found in the lungs and liver at 14 days after intravenous CNP administration were formed by CD68+ macrophages." (PMID 32340313, 2020). "We found that even small granulomas had large clusters of CD11c+CD68+ macrophages that appeared to push T cells out of these regions and impinged on germinal centers, but also disrupted nearby HEV and lymphatic vessels." (PMID 30383808, 2018). "In the EAO testis, however, some CD68+ macrophages in the vicinity of granulomas were positive for Gal-1 too." (PMID 29487346, 2018). "Macrophage (CD68) staining was also prevalent within caseous granulomas but frequently appeared in a pattern surrounding dense neutrophil staining." (PMID 27462092, 2016). "In both OFG and CD, granulomas are characterised by the presence of multinucleated giant cells of macrophage origin that express CD68 molecules." (PMID 25350593, 2014). "Positive signals for CD68 expression were also observed in suspected granuloma occasionally found in the lung sections of the 103.5 and 177.5 mg/kg treated mice." (PMID 23593469, 2013). "Discrete granulomas, composed of HLA-DR+/CD68+ macrophages and giant cells, were seen in cases of pseudotumor and in three cases of component loosening." (PMID 19995315, 2009). "The granulomas consisted of central CD68+ macrophages surrounded by a mantle of CD5+ T-lymphocytes, with some T-lymphocytes infiltrating the granulomas." (PMID 18477401, 2008).
Granuloma (continued). "Therefore, immunohistochemistry was used in this work to evaluate the expression of CD68, iNOS, and HLA-DR in different stages of TB granulomas from naturally infected cattle with tuberculosis." (PMID 37865747, 2023). "The number of CD68+ cells dropped as the granuloma developed." (PMID 37865747, 2023). "Immunohistochemistry of the lung granulomas of huNRG and huDRAG-A2 mice following intranasal infection with the H37Rv strain of Mtb revealed that both human CD4+ T cells and CD68+ macrophages were involved in the formation of granulomas and the containment of the mycobacterium." (PMID 36146734, 2022). "However, significant differences were seen in category 1 granulomas with CM possessing a higher percentage of CD68+ cells (P=0.0152) and in category 6 granulomas where a higher percentage were noted in RM compared to CM (P=0.0166)." (PMID 35069548, 2021). "Furthermore, the number of CD68+ cells in category 4 and 5 granulomas in CM was significantly higher than that in RM at 4 wpc and also higher than the number of CD68+ cells present at 12 wpc in RM." (PMID 35069548, 2021). "Strong TSPO and CD68 co-staining was observed for macrophages in granulomas." (PMID 34150670, 2021). "The CD68 antibody was expressed weakly by epithelioid macrophages and multinucleate giant cells in the inner layer of granulomas while it was expressed strongly by circulating monocytes, Kupffer cells, and macrophages located at the periphery of granulomas and in portal spaces." (PMID 34679889, 2021). "Interestingly, in inflamed testis Gal-1 was also detected in a few CD68+ macrophages located in the vicinity of granulomas." (PMID 29487346, 2018). "CD68-expressing macrophages were seen distributed in the connective tissue including granulomas." (PMID 25350593, 2014). "In addition CD68 positive langhans and foreign body giant cells, granulomas and small CD20 positive B-cell clusters were found." (PMID 21980547, 2011). "Our results suggest a polarization to the pro-inflammatory environment and increased expression of CD68+, iNOS+, and HLA-DR+ macrophages in the early stages of granulomas (I, II), which may play a protective role in the immune response of naturally infected beef cattle with tuberculosis." (PMID 37865747, 2023). "For centrally necrotizing granulomas, a stringent stratification was evident, with an eosinophilic necrotic core consisting of dead and dying cells that was adjacent to regions of neutrophils, surrounded by a rim of foamy macrophages staining less intensely with eosin and positive for CD68." (PMID 34871095, 2022). "Co‐staining of CD68 and CHIT1 in giant cells subsequently identified CHIT1 as a pure giant cell marker in granulomas of SaM." (PMID 40928208, 2025). "In NTMD and TB, CD68 and CD206 were primarily expressed by granuloma epithelioid macrophages, while CD163 was expressed by interstitial scattered macrophages." (PMID 41189710, 2025). "Correlation analysis of positivity rates for CD68, CD86, CD163, and CD206 reveals a significant correlation between CD68 and CD206 in NTMD, primarily expressed in granulomas." (PMID 41189710, 2025). "The granulomas were comprised of CD4+ and CD68+ cells, indicating that they formed by the accumulation of CD4+ T-lymphocytes and macrophages." (PMID 33602264, 2021). "BCG infection resulted in substantial splenomegaly at day 18 and to a lesser extent at day 30 post infection, with CD68-positive, BCG containing granulomas in the spleen and liver." (PMID 33795674, 2021). "Epithelioid macrophages exhibiting M1 phenotype (CD68+CD163-) predominantly present in granulomas of TT patients, whereas macrophages in LL granulomas are foamy and mainly exhibit the M2 phenotype (CD68+CD163+)." (PMID 32373110, 2020). "In macaque and human granulomas, proinflammatory macrophage expressing CD163, CD68, HAM56, and iNOS are observed predominantly in the inner region of the lesions granulomas." (PMID 32544188, 2020).
Granuloma (continued). "In untreated conditions, granulomas were composed of 14.19 ± 2.43% of CD4+ T cells, 12.51 ± 2% of CD8+ T cells, 2.84 ± 0.57% of B cells, and 11.18 ± 1.81% of CD68+ macrophages." (PMID 31475008, 2019). "Levels of Cd68, Inos, Cxcr3, Tcrb, and Ifng transcripts were higher in NOG than in the center (GC) or the rim (GO) of the large and the smaller encapsulated granulomas (SG)." (PMID 31015452, 2019). "In the sarcoidosis group, granulomas were mainly observed in the inner retinal layer filled with CD4+ cells and CD68+ cells, indicating the Th1 immune response." (PMID 29123243, 2017). "Granulomas were mainly comprised of CD4+ cells and CD68+ cells, indicating that the granulomas were formed by accumulation of CD4+ T lymphocytes and macrophages." (PMID 29123243, 2017). "To determine the effect of coinfection on the cellular response within granulomas, we next investigated the numbers of CD3+, CD4+, and CD8+ T cells, monocytes (CD68 coverage), and neutrophils (CD15 coverage)." (PMID 27462092, 2016). "Double staining for CD205 and CD68 revealed that CD205+ cells also expressed CD68, confirming the expression of CD205 in granuloma cells." (PMID 23464965, 2013). "Many S-100+, CD68+, CD163+, CD204+, Fascin+, HLA-DR+, and T cells were found in and around granulomas." (PMID 22588497, 2012). "The marrow granuloma in our case was positive for T cells (CD45, CD3, CD4, and CD8), histiocytes (CD68) and few plasma cells (CD138)." (PMID 17594503, 2007). "A diverse array of innate immune cells, including mast cells (MC) (cluster 20: HDC, CPA3, KIT), dendritic cells (DC) (cluster 23: CLNK, WDFY4, FLT3), neutrophils (FCGR3B, FFAR2, CSF3R), and macrophages (CD68, CD163, C1QA/B/C), was also present in these granulomas." (PMID 40772762, 2025). "Echocardiography-guided pericardiocentesis yielded serosanguinous fluid that fulfilled exudative criteria, and cytology demonstrated CD68-positive macrophages, with no granulomas or malignant cells." (PMID 40861729, 2025). "These granulomas displayed greater organization than the lesions in the early phase but lacked a defined outer lymphocyte layer and were encased in CD68+ phagocytes." (PMID 39807873, 2025). "In histological staining of granuloma regions, Relm-α was abundantly expressed in IL-4c-treated Mac-STAT6 mice, more prominent than in the PBS or STAT6ko controls and co-staining with CD68 and DAPI confirmed Relm-α expression in AAMs with similar frequency in Mac-STAT6 and WT mice." (PMID 37018382, 2023). "In contrast, iNOS was abundantly expressed around the CD68+ core of the granulomas, although we were not able to fully characterize the phenotype of iNOS-producing cells." (PMID 35092727, 2022). "CD68+ granulomas with well-defined borders were less frequent in TB/HIV–co-infected lymph nodes and CD68+ cells were confined inside the M. tuberculosis granulomas, whereas CD163+ cells were located at the periphery, surrounding CD68+ macrophage clusters." (PMID 35092727, 2022). "In vivo analysis of α-MSH-treated granulomas in sarcoidosis mice model revealed a numerical decrease in all measured leukocytes and cytokines, with a statistically significant reduction in CD45+CD68 and CD45+CD3+CD8 in granuloma + α-MSH group relative to the granuloma group." (PMID 35717488, 2022). "Beyond the TB context, CD68+ macrophages expressing DC-SIGN were preferentially detected in granuloma lesions in lepromatous leprosy, as well as in granuloma-like structures in pathological conditions of dermatological diseases, like granuloma annulare and necrobiosis lipoidica." (PMID 29946317, 2018). "Detailed investigation of the size of the hepatic granulomas by means of CD68 staining confirmed the presence of granulomas in Npc1mut-tp mice, while being absent in Npc1wt-tp mice." (PMID 28970532, 2017).
Granuloma (continued). "Whole-slide imaging of hematoxylin and eosin, acid-fast bacilli (AFB), and chromogenic staining for HIV p24, CD3, CD4, CD8, CD15, CD68, interferon γ (IFN-γ), IFN-α, TNF, and IL-10 were used to visualize phenotypic differences within all granulomas and the entire LN section." (PMID 27462092, 2016). "Immunohistochemical staining for CD68 showed a large number of CD68-positive macrophages in the non-necrotic granulomas and the surrounding regions of caseous necrosis." (PMID 26091535, 2015). "Both OFG and CD belong to the group of granulomatous diseases, characterised by the presence of non-caseating granulomas consisting of multinucleated giant cells expressing CD68 molecules." (PMID 25350593, 2014). "Many S-100+, CD68+, CD163+, CD204+, Fascin+, and T cells were found in and around granulomas." (PMID 22588497, 2012). "CD68+ cells were found principally in the reactional granuloma (95%) and some in the dermis (40%) and the reactional biopsies had significantly fewer CD68+ cells than the non-reactional biopsies (p<0.001)." (PMID 22180790, 2011). "We identified calprotectin+ myeloperoxidase+ CD11b+ neutrophils, CD14+/CD68+ monocytes/macrophages, CD3+ T cells, CD3-CD7+ NK cells, CD20+ B cells, CD3+ TCRγδ+ T cells, CD117+ ILC, cytokeratin+ epithelial cells and undefined cells with heterogeneous distribution across all 28 granulomas." (PMID 40749077, 2025). "However, no granuloma structure was observed in the lung section of the uninfected mice, even though a low proportion of cells expressing the human CD68+ and CD19+ surface markers was observed in the lung sections from uninfected mice." (PMID 38799434, 2024). "Double immunolabeling of CD3 and CD68 confirmed results obtained by in situ sequencing, as CD3+ cells located both in 4′,6-diamidino-2-phenylindole (DAPI)-rich and surrounding, DAPI-lighter areas of the lesion, whereas CD68+ located in DAPI-light granuloma areas." (PMID 31015452, 2019). "Immunohistochemical staining for CD68 showed focally intense infiltration of the lamina propria by numerous CD68(+) histiocytes that is in accordance with the immunophenotype of conventional lichen planus, but no granulomas." (PMID 29680851, 2018). "Pearson’s correlation among the examined markers in the granuloma and cyst groups revealed a negative correlation present among TGF-β1 and CD68 (r = -0.8803, p < 0.05; r = -0.1389, p < 0.05, respectively)." (PMID 40217194, 2025). "The presence of CD68+ macrophages and CD138+ plasma cells was similar in periapical cysts and granulomas and the presence of these cells did not correlate with clinical and image data from both groups." (PMID 29075406, 2017).